RNU6-80P (RNA, U6 small nuclear 80, pseudogene)
Synonyms: RNU6-80
Gene: Small nuclear RNA gene on chromosome 13 (72,706,017 to 72,706,123, reverse strand). Ensembl gene ENSG00000206922.
Homologues: Orthologues: chimpanzee U6 (97% identical), guinea pig U6 (91% identical). Paralogues in human: RNU6-21P (94% identical), RNU6-1 (92% identical), RNU6-144P (92% identical), RNU6-15P (92% identical), RNU6-2 (92% identical), RNU6-20P (92% identical), RNU6-3P (92% identical), RNU6-40P (92% identical), RNU6-4P (92% identical), RNU6-5P (92% identical), RNU6-61P (92% identical), RNU6-6P (92% identical), and 1286 more.